ZEB2 (zinc finger E-box binding homeobox 2)
Diseases named in the same sentence as ZEB2 in open-access papers (continued):
Sharing a sentence is not in itself a finding about the gene and the disease.
lung cancer (continued). "In addition, in patients’ samples, we also found increased p-AKT, p-PI3K, ZEB2, and PD-L1 levels from lung cancer patients with low BATF2 expression." (PMID 37777155, 2023). "Indeed, ZEB1 and ZEB2 exhibited positive correlation with GSDME transcript across 188 CCLE lung cancer cell lines." (PMID 34901025, 2021). "Moreover, in vitro and in vivo analyses showed that miR‐132‐3p‐3p downregulation via DNA methylation promoted tumorigenicity of lung cancer by directly regulating ZEB2." (PMID 32500672, 2020). "In addition, elevated miR‐132‐3p expression, reduced expression of its targeted gene (ZEB2), and decreased cell proliferation was observed in lung cancer cells treated with DNA methyltransferase inhibitor." (PMID 32500672, 2020). "miR‐132‐3p‐3p downregulation via DNA methylation could promote tumorigenicity of lung cancer by directly regulating ZEB2." (PMID 32500672, 2020). "miR‐132‐3p could act as a tumor suppressor gene whose downregulation contributes to the progression of lung cancer by directly targeting ZEB2." (PMID 32500672, 2020). "Furthermore, the loss of LKB1 in lung adenocarcinoma cells activated TEAD, which directly transcribed ZEB2 and repressed DNp63 to regulate cell fate and lineage conversion in lung cancer progression." (PMID 31212916, 2019). "Similarly, miR-200c, miR-203 and miR-218 increase CDDP-sensitivity via targeting ZEB2 in gastric, nasopharyngeal and lung cancers." (PMID 29849953, 2018). "Additionally, over-expressing or silencing ZEB2 was able to elevate or inhibit the migration and invasion of lung cancer cells, parallel to the effect of miR-132 on the lung cancer cells." (PMID 24626466, 2014). "Also, the same result about the mRNA levels of ZEB2 was observed in metastatic lymph node tissues, relative to the primary lung cancer tissues." (PMID 24626466, 2014). "However, a previous study showed that uc.77 regulates ZEB2 in human lung cancer." (PMID 34094975, 2021). "Among the many predicted targets, seven genes (SOX4, ZEB2, AVL9, PTPN9, RAB22A, ITGB8 and SIX1) that have been reported to play an oncogenic role in lung cancer were further analyzed." (PMID 35287543, 2022). "Studies have shown that H19 is highly expressed in lung cancer tissues and cell lines, promotes lung cancer cell growth, migration, and invasion, and upregulates the expression of ZEB1 and ZEB2 to further promote EMT." (PMID 36686745, 2022). "Upregulation of c-Myc molecule in turn promoted the expression of ZEB1, ZEB2, and SNAIL gene, which ultimately enhanced epithelial to mesenchymal transition (EMT) and lung cancer metastasis." (PMID 34168109, 2021). "Fourth, miR200c is also known to target ZEB2, which can inhibit EMT in lung cancer especially A549 cells." (PMID 28727734, 2017). "Then, we examined the mRNA or protein expression of ZEB2 in several NSCLC cells, as well as 45 cases of primary lung cancer tissues and metastatic lymph node tissues." (PMID 24626466, 2014). "In lung cancer, miR-138-5p inhibition could promote carcinogenesis and progression by targeting E2F3, CDK8, ZEB2, PD-L1, and PD-1, and the present results displayed that miR-138-5p is downregulated in LUSC tissues and cells." (PMID 35635595, 2022). "For example, while miR-218 suppresses protein levels by targeting SLUG and ZEB2 in lung cancer, it does not have such an effect on ZEB1." (PMID 35201505, 2022). "Not surprisingly, accumulating evidence demonstrated that ZEB2 behaves as an oncogene through promoting the metastasis of lung cancer cells." (PMID 34839824, 2021).
ovarian carcinoma (48 papers, 2014 to 2025). A malignant neoplasm originating from the surface ovarian epithelium. "The ZEB2/E-cadherin ratio has been reported to be positively associated with tumor invasiveness and poor prognosis in breast and ovarian cancer." (PMID 25435948, 2015). "However, the role of EMT and MET related events associated with ZEB1, ZEB2, E-cadherin, vimentin and miR-200 family is highly complex, which certainly requires further investigation in the context of endometriosis and ovarian cancer." (PMID 26819681, 2015). "Regarding ZEB2, the lncRNA-HOTTIP/miR-205/ZEB2 axis has a substantial role in determining the cisplatin resistance of ovarian cancer cells." (PMID 39967908, 2025). "circCRIM1 was implicated in promoting ovarian cancer progression by acting as a competitive endogenous RNA (ceRNA) for the host gene CRIM1 and targeting the miR-383-5p/ZEB2 axis." (PMID 36287121, 2022). "This study investigated the expression of zinc finger E-box binding homeobox 2 (ZEB2), its prognostic significance in various cancers, and the correlation between ZEB2 and infiltrating immune cells and ZEB2-related proteins in ovarian cancer (OV)." (PMID 35723302, 2022). "While ZEB2 worked as oncogenic genes in ovarian cancer to drive EMT transition, tumorigenesis and peritoneal metastasis." (PMID 34847936, 2021). "CircCRIM1 bond with miR-145-5p to work as competing endogenous RNA (ceRNA) of CRIM1, and circCRIM1 bond with miR-383-5p to improve the expression of ZEB2 in ovarian cancer." (PMID 34847936, 2021). "The study found that ZEB2 expression in ascites of patients with high-grade serous ovarian cancer was higher than that of primary ovarian cancers." (PMID 34847936, 2021). "ZEB2 positively regulated the proportion of CD133+ cancer stem-like cells in epithelial ovarian cancer cells and promote the tumorigenesis and peritoneal metastasis capacity of CD133+ cancer stem-like cells." (PMID 34847936, 2021). "In this study, we investigated the effects of miR-200a/ZEB2 on the invasion of ovarian cancer stem-like cells (CSLCs) by regulating the expression of ZEB2 in ovarian cancer cell lines." (PMID 34211089, 2021). "In a word, circCRIM1 worked as ceRNA of CRIM1 through miR-145-5p, and bond with miR-383-5p to improve ZEB2 to play the cancer-promoting roles in ovarian cancer." (PMID 34847936, 2021). "Taken together, circCRIM1 bond with miR-383-5p to up-regulate ZEB2 in ovarian cancer and played the cancer-promoting roles." (PMID 34847936, 2021). "To explore the potential mechanisms of ZEB2 in EOC-CSLC-initiated peritoneal metastasis, we analysed ZEB2 expression in human ovarian cancer cell lines and their metastatic daughter lines (SKOV3/SKOV3-IP and HEY/HEY-A8)." (PMID 34211089, 2021). "The gene DLC-1 is a tumor suppressor, and ZEB2 is a transcriptional repressor, which have been shown to be downregulated in ovarian cancers compared to normal tissues." (PMID 32316405, 2020). "In ovarian cancer, members of the miR-200 family have been implicated with EMT in which ZEB1 and ZEB2 were their targets." (PMID 32316405, 2020). "In a previous study, miR-101 had been shown to suppress EMT by targeting ZEB1 and ZEB2 in ovarian carcinoma." (PMID 30098599, 2018). "In previous studies, ZEB2 promoted stem cell properties in prostate, head and neck, and ovarian cancers." (PMID 27589832, 2016). "ZEB1 and ZEB2, validated targets of miR-141 and miR-200c, contribute to epithelial- mesenchymal transition and cancer cell migration in cancer cell lines and ovarian cancer specimens." (PMID 25815280, 2015). "We demonstrated a role of ZEB2 in migration and anchorage-independent cell growth in ovarian cancer, as shown by ZEB2 silencing." (PMID 26136338, 2015). "We showed that ZEB2 mRNA overexpression is associated with poor outcome, and that concomitant overexpression of nuclear ZEB2 and cytoplasmic Hur at protein level correlates with shorter progression-free-survival and overall survival in ovarian cancer patients." (PMID 26136338, 2015).
ovarian carcinoma (continued). "A similar correlation between ZEB2 expression and prognosis was found in different cancer types, including ovarian cancer." (PMID 26136338, 2015). "The prognostic meaning of ZEB2 expression in ovarian cancer patients is a significant finding of the current study." (PMID 26136338, 2015). "In order to expanding the study of ZEB2 role in ovarian cancer, the expression of ZEB2 gene was firstly assessed in a panel of ovarian adenocarcinoma cell lines (A2780, Hey, SKOV3, SKOV6, OV2774, OVCAR3), along with additional EMT markers." (PMID 26136338, 2015). "Analysis of ZEB2 and HuR expression was assessed by immunohistochemistry in a large series of ovarian cancer patients." (PMID 26136338, 2015). "Analysis of ZEB2 and HuR expression in ovarian cancers revealed that nuclear ZEB2 is localized in tumor leading edge and co-localizes with cytoplasmic HuR." (PMID 26136338, 2015). "The aim of our study was to further analyze the role of ZEB2 in the development of ovarian cancer and to define its prognostic significance." (PMID 26136338, 2015). "In a series of 143 ovarian cancer patients high expression of ZEB2 mRNA significantly correlated with a poor prognosis in term of both overall survival and progression- free survival." (PMID 26136338, 2015). "Previous studies have identified that an increased ZEB2/E-cadherin ratio positively correlates with invasive disease and poor prognosis in breast and ovarian cancers." (PMID 24885194, 2014). "Additionally, the positive correlation between HK2 and fibronectin, MMP9, CHD2, Vemintin, ZEB1 and ZEB2 in human ovarian cancer were also confirmed from the GEPIA online database." (PMID 35953860, 2022). "CircCRIM1 also promotes the tumorigenesis of ovarian cancer by targeting the miR-383/ZEB2 axis." (PMID 36071480, 2022). "Additionally, the positive correlation between HK2 and fibronectin, MMP9, CHD2, Vimentin, ZEB1 and ZEB2 in human ovarian cancer were confirmed from the GEPIA online database (p < 0.05)." (PMID 35953860, 2022). "It bond with miR-383-5p to improve the expression of ZEB2 in ovarian cancer." (PMID 34847936, 2021). "Among those factors with a significant reduction in their mRNA levels, we noticed that EMT-associated transcription factors ZEB1 and ZEB2 were much lower in ISL-treated SKOV3 cells than untreated ones, further indicating the deterrence of EMT by ISL in ovarian cancer cells." (PMID 31623144, 2019). "Recent observations have provided convincing evidence to suggest that miR-200 family members (miR-200a, miR-200b, miR-200c, miR-141, and miR-429) and miR-205 can activate EMT by targeting the EMT drivers ZEB1 and ZEB2 in various cancer types, including ovarian cancer." (PMID 27612152, 2016). "To further investigate the mechanism by which C17orf91 elicited its oncogenic role, we explored whether C17orf91 could regulate key pro-metastatic genes, such as KLF8, MYC, SNAI2, TWIST1, ZEB1 and ZEB2 in ovarian cancer." (PMID 27535740, 2016). "Moreover, the nuclear expression of ZEB2 was found to be of relevant prognostic significance in ovarian cancer." (PMID 26136338, 2015). "Similarly, in ovarian carcinoma the presence of tumor layers with different ZEB2 expression could reflect the phenotypic plasticity within the same tumor and support the pivotal role of EMT-TFs during ovarian carcinogenesis." (PMID 26136338, 2015). "The Hey cell line express ZEB2 protein and lowest levels of miR-200c and miR-141, suggesting that these two members of the miR-200 family could have a critical role in ZEB2 repression in other ovarian cancer cells." (PMID 26136338, 2015). "DAB2 expression had significant positive correlations with mesenchymal markers (ZEB2, TGFβ1, SNAI2, ZEB1, FN1, MMP2, TWIST1 and MMP3) and CSC markers (CD44 and MYD88) in ovarian cancer cell lines (CCLE) and tissues (TCGA: RNA sequencing and microarray)." (PMID 37815603, 2023).
ovarian carcinoma (continued). "In ovarian cancer cells, overexpressing of HK2 enhanced cell motility by inducing of EMT-related proteins, such as CDH2, fibronectin, MMP9, ZEB1, ZEB2 and vimentin." (PMID 35953860, 2022). "Among these markers, ZEB2, the Zn-finger EMT transcription factor, is highly expressed in metastatic ovarian cancer cells compared to in situ lesion cells, indicating that ZEB2 plays an important role in ovarian cancer peritoneal metastasis." (PMID 34211089, 2021). "miR-374b suppresses the migration and invasion of bladder cancer cells by targeting ZEB2, an EMT-inducing transcription factor, and suppresses cell proliferation, migration, and EMT in ovarian cancer by targeting FOXP1." (PMID 32674274, 2020). "Re-expression of miRNAs of the miR-200 family reduced expression of its target genes, including ZEB1, ZEB2, FN1 and class III β-tubulin (TUBB3), and inhibited ovarian cancer cell migration and invasion." (PMID 28399108, 2017). "In conclusion, our findings provide evidence for a role of ZEB2 and HuR in EMT progression and development of an aggressive phenotype in ovarian cancer." (PMID 26136338, 2015). "Overall our results demonstrated that both ZEB2 and ZEB1 contributed to the migratory and anchorage-independent cell growth abilities in Hey ovarian cancer cell line." (PMID 26136338, 2015). "In conclusion, we demonstrated for the first time that miR-101 can directly target ZEB1 and ZEB2, resulting in suppression of the EMT in ovarian carcinoma." (PMID 24677166, 2014). "This is supported by the finding of elevated E-cadherin and reduced ZEB1 in metastatic epithelial ovarian cancer, as well as by our findings of overexpressed miR-200 family members and underexpression of ZEB1 and ZEB2 in metastatic HGSC." (PMID 24512620, 2014). "To demonstrate that miR-101 is an endogenous regulator of ZEB1 and ZEB2 in ovarian carcinoma cells, we transfected SKOV3 ovarian cancer cells with miR-101 or miR-Ctrl followed by measurement of ZEB1 and ZEB2 mRNA and protein at 48 h after transfection." (PMID 24677166, 2014). "Zinc finger E-box binding homeobox 2 (ZEB2) was ultimately shown to be the miR-205 gene target, completing the analysis of HOTTIP-miR-205-ZEB2 as the novel axis that is functionally engaged in determining the resistance of ovarian cancer cells to cisplatin." (PMID 40616679, 2025). "ZEB1 has been upregulated by TGF-β and ZEB2 by TGF-β treatment of ovarian cancer cells." (PMID 36766756, 2023). "In this study, further study also demonstrated that HK2 could elevate the expression of EMT-related factors in human ovarian cancer cell, like fibronectin, MMP9, CHD2, Vemintin, ZEB1 and ZEB2." (PMID 35953860, 2022). "We demonstrated that ZEB2, the transcription factor of epithelial–mesenchymal transition (EMT), was upregulated in ascites cells from HGSOC patients and in CD133+ cancer stem-like cells (CSLCs) from epithelial ovarian cancer (EOC) cell lines." (PMID 34211089, 2021). "The miR-200 family plays a critical role in the suppression of epithelial-to-mesenchymal transition (EMT) and tumor cell migration, invasion, and metastasis by directly targeting ZEB1 and ZEB2 transcription factors and the level of miR-200s are important regulators of EMT in ovarian cancer cells." (PMID 29389895, 2018). "In conclusion our findings indicated that nuclear ZEB2 may enhance progression of EMT transition and acquisition of an aggressive phenotype in ovarian cancer." (PMID 26136338, 2015). "Finally, ZEB2 was identified as the gene target of miR-205, thus completing the elucidation of HOTTIP-miR-205-ZEB2 as the novel axis which is functionally involved in the determination of cisplatin resistance in ovarian cancer cells." (PMID 34322490, 2021). "Similarly, ChIP-seq experiments showed no binding of GRHL2 to the Zeb1 or Zeb2 promoters in kidney, placenta, ovarian cancer or lung epithelial cells." (PMID 32005677, 2020).
ovarian carcinoma (continued). "Higher expression of ZEB1 and ZEB2 were found in diverse types of cancer including ovarian carcinoma, suggesting that the two factors may play an essential role in EMT of ovarian carcinoma." (PMID 24677166, 2014).
prostate carcinoma (47 papers, 2011 to 2025). A carcinoma that arises from epithelial cells of the prostate gland. "Also, ZEB1 expression was associated with prostate cancer (PCa) progression and metastasis, while Twist1 plus ZEB2 expression was related to early disease recurrence in HCC." (PMID 28590039, 2017). "According to the contradictory findings, SNAI1 gene expression was higher in gastrointestinal tumor tissue than in normal tissues, and ZEB2 expression was significantly higher in prostate cancer tissue than in BPH tissue." (PMID 40693059, 2025). "The results showed that the expression levels of CDH2, SNAI1, ZEB1, and ZEB2 were significantly downregulated in prostate cancer compared to controls, while the expression of CDH1 was significantly upregulated." (PMID 40693059, 2025). "Overexpression of both ZEB1 and ZEB2 has been reported in a number of cancers, including prostate cancer, breast cancer, gynecological cancers, head and neck cancers, and specifically in oral squamous cell carcinoma." (PMID 38751602, 2024). "ZEB2 is a direct target of miR-200c-3p that is downregulated in prostate cancer, which results in EMT." (PMID 34439151, 2021). "Overexpression of miR-200c-3p significantly suppresses the formation of migration and invasion in prostate cancer cells via targeting ZEB2." (PMID 34524611, 2021). "In prostate cancer, overexpression miR-203 controls proliferation, migration and invasion by directly targeting ZEB2, Bmi-1, survivin and LASP1." (PMID 29228583, 2017). "This miRNA was found to be further active in prostate cancer cells, where it was found to limit invasion, migration, EMT, and the stemness of prostate cancer cells via the repression of ZEB2." (PMID 26784241, 2016). "MiR-205, which is induced by p63, was reported to inhibit EMT by targeting ZEB1 and ZEB2 in breast cancer and prostate cancer." (PMID 24598126, 2014). "Our model identified several transcription factors associated with prostate cancer metastasis, such as ETS2, HOXC4, STAT3, STAT5B, SOX4 and ZEB2." (PMID 23782521, 2013). "Similarly, this type of study previously demonstrated the miR-200c-3p/ZEB2 regulatory loop in prostate cancer progression." (PMID 40693059, 2025). "The ZEB1/deltaEF1 and ZEB2/SIP1 transcriptional suppressors of E-cadherin and the miR-200 family are components of a signaling network, and the latter has been found to regulate PDGF-D-linked EMT in prostate cancer cells." (PMID 40801639, 2025). "Moreover, lncRNA activated in prostate cancer progression (lncAPP) accelerated prostate cancer progression by competitively sponging miR-218 to enhance ZEB2 and CDH2 expression." (PMID 32351538, 2020). "In this study, we investigated for the first time the role of both ZEB1 and ZEB2 in docetaxel‐resistant prostate cancer and provide strong evidence for ZEB1, through its transcriptional repression of E‐cadherin to be a driver of both EMT and docetaxel resistance." (PMID 28133913, 2017). "Similarly, the mutual control of miR-145 and ZEB2 contributes to prostate cancer progression and metastasis, wherein ZEB2 directly represses the transcription of miR-145, which in turn represses ZEB2." (PMID 27992370, 2017). "However, the roles of Akt and Zeb2 in prostate cancer progression and recurrence are still unclear and worth further investigation in our future work." (PMID 27455254, 2016). "Thus, in order to identify the protein mediators downstream to PlexinD1, we analyzed the expression of EMT transcription factors Snail, Slug, Twist, Zeb1 and Zeb2 in PC3 prostate cancer cells." (PMID 27749937, 2016). "Moreover, miR-200 regulated PDGF-D-mediated EMT partly through down-regulation of ZEB1, ZEB2 and Snail, and up-regulation of E-cadherin in prostate cancer cells." (PMID 24158561, 2013). "For example, miR-141 could promote prostate cancer cell proliferation through inhibiting KLF9 expression while it can also inhibit vascular smooth muscle cell proliferation through targeting PAPP-A or ZEB2 to suppress HCC progression." (PMID 29029425, 2017).